IL6 (interleukin 6)
Diseases named in the same sentence as IL6 in open-access papers (continued):
Sharing a sentence is not in itself a finding about the gene and the disease.
Obesity (continued). "The main findings suggest that the KD, as a source of ketone bodies in the blood, improves glutamate activity by reducing obesity, which is associated with insulin resistance and dyslipidemia, promoting central inflammation (particularly through an increase in interleukins IL-1β, IL-6, and IL-17)." (PMID 37693246, 2023). "In addition, elevated IL-6 is associated with increased cancer mortality in patients with obesity." (PMID 36670988, 2023). "In addition to an increased burden on the skeletal system, particularly the joints, which is a natural consequence of excessive weight, the production of interleukin-6 (IL-6) from fat cells predisposes the individual with obesity to a state of chronic mild inflammation." (PMID 36765351, 2023). "Furthermore, TNF-α and IL-6 also have been highlighted to be responsible for the association between obesity and asthma, since they could enhance the production of IL-4 and IL-5, being both found raised in eosinophilic asthma." (PMID 37920579, 2023). "Furthermore, chronic low-grade inflammation and increased levels of circulating pro-inflammatory cytokines associated with obesity, such as leptin, tumor necrosis factor a, and interleukin 6, may impair immune response and affect the lung parenchyma." (PMID 37373748, 2023). "In human bronchial epithelium, adiponectin also dampened the inflammatory response among others by inhibiting IL-6, and low circulating adiponectin levels in individuals with obesity may therefore contribute to SARS-CoV-2 susceptibility and increase the severity of the infection." (PMID 36509969, 2023). "Obesity is associated with a pro-inflammatory state and increase in circulating concentrations of cytokines, including insulin-like growth factor-1, hepcidin, tumor necrosis factor-alpha and interleukin-6 (IL6); such are considered crucial to the pathogenesis of MM." (PMID 37790413, 2023). "Besides, IL-6 levels were only associated with obesity in female patients treated with clozapine." (PMID 37370004, 2023). "Furthermore, obesity is associated with impaired ovarian function, poor oocyte quality and decreased reproductive performance by elevated proinflammatory cytokines, such as interleukin 6 (IL-6) and TNFα as well as oxidative stress." (PMID 35897496, 2022). "Thus, high circulating levels of IL-6 could reflect the intensity of obesity-associated chronic and systemic inflammation, which in turn might contribute to the development of atherosclerosis and CHD, both directly and by reducing HDL cholesterol levels." (PMID 36430774, 2022). "Further research that includes AGP and other APPs and adipocytokines may aid in understanding which are most useful for iron assessments, as inflammatory biomarkers, such as IL-6 and α-1-antitrypsin, have been shown to be important in characterizing inflammation associated with obesity." (PMID 36475018, 2022). "However, IL-6 deficient mice develop insulin resistance and mature-onset obesity." (PMID 36230963, 2022). "Taken together, it is still unclear whether IL-6 is a primary trigger for the development of obesity and insulin resistance or whether it is actually required to counteract the increased inflammation associated with obesity." (PMID 36387898, 2022). "Maternal prepregnancy obesity or excessive weight gain during pregnancy would lead to chronic systemic inflammation and placental inflammatory response, causing increased concentrations of pro-inflammatory cytokines such as IL-6, IL-8, tumor necrosis factor-α (TNF-α) and C-reactive protein (CRP)." (PMID 36364875, 2022). "Excess visceral fat developed in obesity has been shown to secrete more adipokines and chemokines that promote insulin resistance, macrophage infiltration and activation, and is associated with elevated inflammatory markers such as interleukin 6 (IL-6) and tumor necrosis factor-α (TNF-α)." (PMID 35276910, 2022). "Furthermore, leptin and IL-6 were associated with individuals with obesity and PD." (PMID 36547041, 2022).
Obesity (continued). "It has been theorized that the observed association of IL1 cytokine family genes with obesity in mice may be due to leptin dysregulation and consequent hyperphagia rather than direct modulation of adipocyte function because Il1r1 and Il6 KO mice develop leptin resistance." (PMID 34834553, 2021). "Obesity is associated with immune responses that lead to a systemic low-grade proinflammatory state derived from an increase in adipocytes, loss of balance with immune cells, and the release of cytokines such as interleukin 6 (IL-6), which decreases adiponectin secretion." (PMID 35010709, 2021). "Since the observed changes could partially be attributed to TNF-α and IL-6 activity, an anti-inflammatory therapy might be a promising early therapeutic prevention option, especially in high-risk patients, such as those suffering from obesity or T2DM." (PMID 34064969, 2021). "Thus, a recent review revealed that the minor allele A of IL-6 rs1800797 gene polymorphism has a protective role against obesity, while the C allele of IL-6 rs1800795 gene polymorphism is associated with increased obesity risk." (PMID 34207683, 2021). "Obesity-associated AT inflammation is characterized by the generation and secretion of multiple inflammatory cytokines and chemokines, including but not limited to interleukin-6 (IL-6), tumor necrosis factor-α (TNF-α), IL-1β, IL-18, and monocyte chemoattractant protein-1 (MCP-1)." (PMID 34680216, 2021). "Finally, to assess the clinical relevance of methylation involved in the obesity-related inflammatory and metabolic alteration, we tested adiposity-associated methylation markers for association with inflammation markers IL-6 and metabolic biomarkers such as lipoproteins." (PMID 34670603, 2021). "Obesity is also associated with the production of several adipocytokines hypothesized to promote oncogenesis, including leptin, tumor necrosis factor-alpha (TNFα), interleukin-6 (IL-6), IL-7, and IL-8." (PMID 33105727, 2020). "MYO3A associations with interleukin-6, cortisol secretion, and BMI-adjusted waist circumference have previously been reported; in other studies, eosinophil counts and characteristics of red blood cells have been correlated with obesity or BMI, and obesity is associated with an inflammatory response." (PMID 32912333, 2020). "However, One possibility that can cause increased systemic IL-6 levels may be due to obesity where accumulation of fat leads to a chronic metabolic inflammatory status." (PMID 32298379, 2020). "We examined whether the serum from mice with GWI and obesity would induce M1 polarization of microglia and release proinflammatory cytokine IL6, a crucial mediator in worsening GWI-associated neuroinflammation, by screening supernatants for the cytokine concentration using ELISA." (PMID 32927823, 2020). "Using both observational and genetic mediation analyses, we show that the impact of the IL-6 pathway on risk of type 2 diabetes due to obesity is modest (3–5%), which challenges a prevailing hypothesis that IL-6 has an important role in the link between obesity and diabetes risk." (PMID 33096487, 2020). "As obesity, induced by a state of high caloric intake, is associated with chronic inflammation, we next examined whether the pro-inflammatory cytokines IL6 and TNFα levels were altered in by HF diet in gWAT, iWAT, iBAT and PAT compared to their chow-fed counterparts." (PMID 32580292, 2020). "Obesity-related HFpEF obtained in our experimental conditions was associated with a subclinical pro-inflammatory status highlighted by significantly increased IL-6 and leptin plasma levels, a trend for increased TNF-alpha and decreased adiponectin/leptin ratio, but without CRP modifications." (PMID 33142857, 2020). "Furthermore, obesity may be associated with an elevated concentration of the immune system markers, for example, IL-6." (PMID 31191300, 2019).
Obesity (continued). "Gain- and loss-of-function studies showed CCL2 and IL-6 expression associate with the frequency of γδ T cells, indicating these cells may originate downstream of primary immune cell and/or adipocyte changes in obesity." (PMID 31379820, 2019). "Obesity as a low-grade chronic inflammation has been associated with tissue hypoxia/necrosis with consecutively upregulation of the pro-inflammatory response via cellular (M1/2 macrophage—Th1/Th2 cells phenotype transformation) and molecular (IL-1β, IL-6, TNF-α) pathways." (PMID 30795781, 2019). "Previous mechanism studies suggested that chronic inflammation contributed to the pathogenesis of obesity; the infiltration and accumulation of macrophages in adipose tissue was demonstrated to be associated with increased tumor necrosis factor-α and interleukin 6 secretion." (PMID 31767029, 2019). "In addition, obesity is responsible for causing systemic low-grade inflammation, particularly by visceral fat, which excretes several different pro-inflammatory cytokines, such as interleukin-6 (IL-6) and TNF-α." (PMID 29757230, 2018). "Similarly, using a network-based pharmacological analysis, mulberry extracts have been proposed to regulate TNF-α, PPARγ, glycogen synthase kinase-3 beta (GSK3B), insulin receptor substrate 1 (IRS1), interleukin 6 (IL-6) and other proteins involved in diabetes and obesity associated complications." (PMID 30577684, 2018). "Severity of obesity is also associated with high blood pressure and is in part attributed to endothelial dysfunction, sympathetic nervous system overactivity, and fat cell inflammation contributing to increases in plasma interleukin-6 and tumor necrosis factor." (PMID 30009058, 2018). "Increased oxidative stress and various pro-inflammatory cytokines and chemokines, including tumor necrosis factor-α (TNF-α) and interleukin-6 (IL-6), which might interfere with anti-inflammatory effects on insulin action, were associated with insulin resistance, obesity, and type 2 diabetes." (PMID 30532735, 2018). "IL-6 signaling is not only required to induce IL-10 expression, but is also involved in T cell differentiation to IL-17-expressing T cells, thereby further complicating the exact definition of cell type specific contributions of inflammatory mediators in obesity and its associated disorders." (PMID 30591653, 2018). "Certain genetic studies proved that different polymorphisms of the IL-6 gene present a key role in transcriptional regulation and influence plasmatic cytokine levels, supporting the fact that this gene interacts with metabolic modulation, resulting in different metabolic conditions, such as obesity." (PMID 30338250, 2018). "In addition to IL-6, impaired myostatin and muscle cytokine signaling may contribute to RA-associated sarcopenic obesity." (PMID 30587230, 2018). "Thus, they suggest that due to increased inflammatory condition, peripheral blood mononuclear cells indicate BDNF and IL-6 expression, which may play a collaborative neuroprotective effect associated with obesity." (PMID 29062839, 2017). "Thus, our data demonstrate differential temporal and tissue-specific functions of IL-6 signalling in T-lymphocytes, as well as the time-dependent importance of the classical and trans-signalling of IL-6 during the development of obesity-associated inflammation and insulin resistance." (PMID 28466852, 2017). "Moreover, the association between IL-6 levels and obesity in T2DM indicates that weight control may be an action adopted for preventing inflammatory status in T2DM." (PMID 28225860, 2017). "Obesity causes chronic inflammation which associates with expression and release of pro-inflammatory cytokines including interleukin-6 and tumor necrosis factor-alpha (TNF-α).16,17 These pro-inflammatory cytokines may cause release of hepcidin from liver or adipose tissue." (PMID 28875005, 2017).
Obesity (continued). "In addition, inflammatory mediators such as C-reactive protein and interleukin-6 may contribute to the obesity-related bladder cancer risk as suggested by positive relation of circulating levels of inflammatory markers to bladder cancer mortality." (PMID 28389625, 2017). "With the knowledge of our current findings, neutralizing IL-6 signalling in T cells could still be considered, though as a short-term therapy, during the early development of obesity or in a weight-loss programme as a combinational therapy to enhance the effectiveness of diet and exercise." (PMID 28466852, 2017). "Furthermore, certain adipokines, such as leptin, are mainly associated with total obesity, whereas others, such as IL-6 and adiponectin may be more closely linked with abdominal obesity." (PMID 27567677, 2016). "WAT releases hormones (leptin, adiponectin, etc.)and cytokines (tumor necrosis factor-α (TNF-α), interleukin 6 (Il-6), monocyte chemoattractant protein-1 (Mcp-1), etc.)that modulate whole-body metabolism, insulin resistance, and the systemic low-grade inflammation associated with obesity." (PMID 28105413, 2016). "Obesity is associated with low grade chronic inflammation and in order to mimic this in human adipose tissue we first investigated whether direct cell interactions between macrophages and adipocytes have an impact on IL-6, IL-8, and MCP-1 expression." (PMID 25926797, 2015). "Obesity has been discovered to be associated with excess adipocyte hypertrophy generating a proinflammatory state through secretion of inflammatory cytokines and chemokines, including interleukin (IL)-1β, IL-6, IL-8, monocyte chemoattractant factor, tumor necrosis factor-α, and C-reactive protein." (PMID 26658675, 2015). "Our data indirectly suggests that interleukin-6 originating from fat tissue may play a role in overweight- and obesity-related CVD, because CRP decreased the BMI-associated CVD risk markedly, and because it is well known that CRP itself is only a marker not a cause of CVD." (PMID 26035431, 2015). "Whereas obesity favors the production of M1 macrophages, which is associated with reduced adiponectin mRNA expression by the infiltrated adipose tissue and elevations in circulating IL-6 and CRP, adiponectin promotes a shift to the M2 phenotype and so is an anti-inflammatory adipokine." (PMID 26516917, 2015). "Obesity is found to be associated with low-grade inflammatory process characterized by the increase in circulating levels of pro-inflammatory cytokines such as transforming growth factor-β1, interleukin-6 and acute-phase protein (haptoglobin) in healthy obese adults." (PMID 27275205, 2015). "Obesity-associated inflammation occurs as a result of immune cell infiltration into the adipose tissue and increased production of pro-inflammatory cytokines such as IL–1β, IL–6 and TNF-α, leading to the pathogenesis of insulin resistance and eventually to the development of type 2 diabetes." (PMID 26437377, 2015). "With levels of circulating IL-6 increasing with weight gain and decreasing upon weight loss, assessment of genetic variations in the IL-6 gene has shown that it is linked to both indices of obesity and perturbations in the homeostatic regulation of glucose and insulin." (PMID 25309775, 2014). "Increased Hsp60 binding and Hsp60-induced IL-6 release by mature adipocytes of NZO mice suggest that enhanced adipocyte reactivity to the stress signal Hsp60 contributes to inflammatory processes underlying diabetes associated with obesity and insulin resistance." (PMID 24672802, 2014). "However, the published findings support our study hypothesis that dietary fatty acids may influence obesity risk and serum lipid levels differently, depending on the IL-6 genotype of the individual." (PMID 24962479, 2014).
Obesity (continued). "Indeed, this type of adipose tissue is able to produce proinflammatory cytokines, such as tumor necrosis factor-alpha (TNF-alpha) and interleukin-6 (IL-6), and it is responsible of the increase of obesity-related CVD risk factors such as dyslipidemia, insulin resistance, and hypertension." (PMID 24966465, 2014). "In addition, the lowest levels of IL-6 in underweight may result of reduced adipose tissue and fatty acids which release inflammation-related adipokines commonly related to obesity-associated pathologies." (PMID 24023413, 2013). "Thus, elevated TNF-α plasma levels are associated with abdominal obesity and an increased risk of myocardial infraction in men, while IL-6 circulating levels increase with obesity and are associated with increased risk for myocardial infarction and new onset type 2 diabetes." (PMID 23484124, 2013). "In addition, the association between high n-6/n-3PUFAs dietary ratio and obesity may account for the high IL-6 and hs-CRP that we found in our OB patients." (PMID 23984354, 2013). "Finally, as pro-inflammatory cytokine production by adipose tissue is a hallmark of obesity, we analysed the production of IL-6 by adipose tissue explants from CAV1+/+ and CAV1−/− mice that had been maintained on a high-fat diet (HFD) or a control diet for 12 weeks." (PMID 23049990, 2012). "A chronic IL-6 stimulation may interfere with the regulation of IL-6 signaling and indeed we here report a down regulation of the IL-6Rα receptor in skeletal muscle biopsies of people with obesity and a deficient downstream IL-6 signaling in DM myocytes." (PMID 22761857, 2012). "In addition, associations with IL-6 persisted after adjustment for age, race and socioeconomic factors but were reduced and no longer statistically significant after adjustment for potential mediators of inflammation such as smoking and obesity." (PMID 21083905, 2010). "Thus, the pleiotrophic effects of chronically elevated IL-6 levels preclude any obvious usefulness in treating obesity or its associated metabolic complications in man, despite the fact that weight reduction may be expected." (PMID 20300479, 2010). "Elevated levels of pro-inflammatory cytokines such as TNF-α, IL-1β, and IL-6 are observed in ovarian conditions including obesity, polycystic ovary syndrome, endometriosis, and reproductive aging." (PMID 41625246, 2026). "Chronic inflammation from obesity is closely related to oxidative stress: oxidative stress in adipocytes has been found to promote insulin resistance and enhance local release of IL-6 and TNF-α that aggravate systemic inflammation." (PMID 41590667, 2026). "Obesity's chronic inflammatory milieu, with elevated IL-6, TNF-α, and CRP, compromises BBB integrity, facilitating immune cell infiltration and neuroinflammation." (PMID 41543809, 2026). "Evidence indicates that IL-6 is an important regulator of metabolic homeostasis and contributes centrally to body weight control, particularly in obesity." (PMID 41362820, 2026). "In humans, newborns of overweight women with gestational diabetes were more likely to display a systemic inflammation manifested by increased levels of IL‐6, IL‐8, ICAM3, TNFR1 and VEGFR2, creating a milieu that predisposes to obesity." (PMID 41085141, 2026). "Women exhibited progressive increases in plasma interleukin (IL)-6 with obesity severity, whereas men with severe obesity demonstrated elevated IL-15 and IL-1rα plasma levels." (PMID 41977491, 2026). "High-dose CU262 in particular brought IL-6/TNF-α down and IL-10 up relative to HFD alone (p < 0.05), indicating an attenuation of obesity-associated systemic inflammation." (PMID 41596930, 2026). "The proteins that were increased in diabetes, including OSM, IL-8, IL-18R, TNFSF14, TNF and IL-6, play roles in obesity, insulin resistance, beta cell function and vascular diabetes complications." (PMID 41175199, 2026).